TTN (titin)
Diseases named in the same sentence as TTN in open-access papers (continued):
Sharing a sentence is not in itself a finding about the gene and the disease.
dilated cardiomyopathy (continued). "Although dilated cardiomyopathy is associated with many genes, truncating mutations observed in the TTN gene are often found." (PMID 35061126, 2022). "TTN variants have been associated with several CVDs, including dilated cardiomyopathy, fatal cardiomyopathy and heart failure." (PMID 35872888, 2022). "The autosomal-dominant hereditary truncating A-band TTN variants (TTNtvs), for instance, are the most frequent genetic cause of dilated cardiomyopathy, identified in up to 25% of familial dilated cardiomyopathy cases." (PMID 36147537, 2022). "TTN had a high carrier frequency (8.24%) in the Chinese population, which is associated with dilated cardiomyopathy." (PMID 36072675, 2022). "The variants of TTN, a new dilated-cardiomyopathy-related gene included in the SF v3.0 list, occupied the largest proportion of those SFs variants." (PMID 36143288, 2022). "Another application for human iPSC-based heart-on-chip platform is the mechanistic investigation of incomplete penetrance in dilated cardiomyopathy caused by titin truncating mutations." (PMID 33614613, 2021). "Originally, RBM20 mutations were discovered to cause the development of dilated cardiomyopathy by erroneous splicing of the gene TTN (titin)." (PMID 33450993, 2021). "Loss of titin leads to dilated cardiomyopathy with systolic and diastolic dysfunction, while titin truncation or deletion of the N2B segment, that impair sarcomeric array, lead to cardiac atrophy with preserved function." (PMID 33419963, 2021). "Familial dilated cardiomyopathy occurs as a problem of sarcomere function, and mutations in the gene encoding for titin (TTN) are known to be one of the main causes." (PMID 33916254, 2021). "Truncation mutations of titin are the most common genetic causes of dilated cardiomyopathy and often lead to a phenotype that presents later in life and is associated with atrial arrhythmias." (PMID 32859027, 2020). "Mutations in the TTN gene that are predicted to truncate the protein prematurely are considered responsible for about 15% to 20% of dilated cardiomyopathy cases." (PMID 33145465, 2020). "Recently, titin-truncating variants (TTNtv), which are predominantly associated with dilated cardiomyopathy (DCM), were associated with early-onset AF." (PMID 32013268, 2020). "Titin truncation variants have been associated with dilated cardiomyopathy and have been found in up to 27% of patients with DCM, making it the largest-known genetic contribution to DCM." (PMID 30742931, 2020). "Different with the phenotypes of ClockΔ19 mice, loss of Bmal1 gave rise to age-associated dilated cardiomyopathy, as a result of altered titin isoform component, change of MYH gene expression, and disrupted sarcomere structure." (PMID 32277346, 2020). "Mutations leading to early termination of titin are the most common genetic cause of dilated cardiomyopathy." (PMID 32859027, 2020). "This phenomenon of a blunted β-adrenergic response at single hiPSC-CMs has been reported in the pathogenic variants of mutations in titin mutations of dilated cardiomyopathy." (PMID 32392813, 2020). "Studies of LV samples from patients with dilated cardiomyopathy or hypertrophic cardiomyopathy or with HFpEF associated with type 2 diabetes indicated that diminished phosphorylation of titin by PKGI contributes to these changes." (PMID 33055420, 2020). "- Titin (TTN) truncation variants are the most frequent cause of dilated cardiomyopathy, one of the main causes of heart failure and heart transplant." (PMID 31849696, 2019). "From these analyses, we demonstrate the direct and prevalent involvement of variants in genes associated with dilated cardiomyopathy and, in particular, titin-truncating variants (TTNtvs) in CCM." (PMID 30987448, 2019).
dilated cardiomyopathy (continued). "In a study of patients with dilated cardiomyopathy caused by mutation in the Titin (TTN) gene, skin fibroblasts from these patients and healthy donors were used to generate iPSC that were posteriorly differentiated into cardiomyocytes." (PMID 31336746, 2019). "Truncating variants in TTN (TTNtv), coding for the largest structural protein in the sarcomere, contribute to the largest portion of familial and ambulatory dilated cardiomyopathy (DCM)." (PMID 31705051, 2019). "In a large study of 312 patients with dilated cardiomyopathy, a truncating titin mutation was present in one-fourth of familial and in 18% of sporadic cases." (PMID 28928965, 2017). "Heart failure was induced in a mouse model that imitates a human titin truncation mutation we found in a patient with dilated cardiomyopathy (DCM)." (PMID 28353642, 2017). "A subset of these carried a second mutation in titin, leading to a more severe dilated cardiomyopathy." (PMID 28262700, 2017). "Mutations in TTN have been reported in about 18% of sporadic dilated cardiomyopathies and 25% of familial autosomal dominant cardiomyopathies and rarely caused hypertrophic cardiomyopathies." (PMID 28018021, 2016). "Truncating titin (TTN) mutations, especially in A-band region, represent the most common cause of dilated cardiomyopathy (DCM)." (PMID 26701604, 2015). "Truncating and/or missense mutations in TTN result in cardiac (dilated cardiomyopathy [DCM]) and skeletal muscle (myofibrillar myopathy) disease." (PMID 26473617, 2015). "Mutations in the giant sarcomeric protein titin (TTN) are a major cause for inherited forms of dilated cardiomyopathy (DCM)." (PMID 26504781, 2015). "Frameshift mutations in the TTN gene encoding titin are a major cause for inherited forms of dilated cardiomyopathy (DCM), a heart disease characterized by ventricular dilatation, systolic dysfunction, and progressive heart failure." (PMID 25759365, 2015). "In this study, we showed that pressure overload by thoracic aortic constriction induces maladaptive hypertrophy with impaired left ventricular function in a mouse model with a TTN truncation mutation we found in a family with dilated cardiomyopathy." (PMID 26504781, 2015). "TTN truncating variants have been described as the major disease gene for dilated cardiomyopathy, accounting for approximately 25% of all cases." (PMID 26504781, 2015). "Mutations that shorten the gene that encodes Titin can cause part of the heart to become enlarged and weakened, a condition called dilated cardiomyopathy." (PMID 26473617, 2015). "The recent discovery of titin mutations being a major cause of dilated cardiomyopathy (DCM) also underpins the importance of mechanosensation and mechanotransduction in the pathogenesis of heart failure." (PMID 24531746, 2014). "Altered granular dynamics lead to mis-splicing of Titin, causing Dilated Cardiomyopathy." (PMID 41596484, 2026). "Interestingly, reduced titin stiffness is associated with longer sarcomere length, and truncating mutations in titin result in dilated cardiomyopathy." (PMID 39976600, 2025). "TTN mutations have been strongly associated with cardiac diseases, especially dilated cardiomyopathy (DCM), which is characterized by systolic dysfunction and ventricular enlargement in the absence of identifiable causes such as ischemic, congenital, hypertensive, or valvular etiologies." (PMID 41190030, 2025). "Furthermore, c.2609G>T p.(Arg870Leu) and c.52903C>T p.(Arg17635*) were identified in MYH7 (associated with hypertrophic cardiomyopathy) and TTN (associated with dilated cardiomyopathys), respectively." (PMID 40699671, 2025). "It is worth noting that FKBP7, PRKRA, and third gene (PLEKHA3, significant with LVM, LVEDV, and LVESV), all lie within a region of chromosome 2 that also includes the gene TTN, which is well established heritable cause of dilated cardiomyopathy, a leading cause of heart failure." (PMID 39670392, 2025).
dilated cardiomyopathy (continued). "Additionally, TTN (titin) mutations, which are also commonly associated with dilated cardiomyopathy, increase the risk of AF by contributing to atrial wall thinning and reducing contractile function, facilitating arrhythmogenic re-entry pathways." (PMID 40207039, 2025). "TTN has definitive gene-disease validity for dilated cardiomyopathy, but in addition, many variants in TTN have been reported in individuals with HCM though the majority are missense without functional data or located in an exon with low percent spliced in (PSI) cardiac tissue." (PMID 39132495, 2024). "Therefore, TTN variants are associated with different genetic diseases, including hypertrophic and dilated cardiomyopathy and several skeletal muscle diseases." (PMID 38381767, 2024). "Mutations in TTN cause dilated cardiomyopathy and are associated with unusual/stellate nuclei." (PMID 38213836, 2024). "Indeed, titin has been implicated in a variety of heart muscle diseases among which dilated cardiomyopathy (DCM) and heart failure with preserved ejection fraction (HFpEF)/diabetic cardiomyopathy (DbCM) are the most prominent." (PMID 38660537, 2024). "However, TTN truncating variants are a common cause of dilated cardiomyopathy, however their penetrance for dilated cardiomyopathy in general populations is low." (PMID 37612666, 2023). "TTN, which encodes titin, is a causative gene of dilated cardiomyopathy." (PMID 40225163, 2023). "Mutations in TTN were both existed and predicted to be causative in dilated cardiomyopathy and KC, indicating that there might some similar molecular mechanism between them." (PMID 36118869, 2022). "TTN mutations are also associated with dilated cardiomyopathy." (PMID 35819063, 2022). "TTN is a well-established causal gene for dilated cardiomyopathy." (PMID 33145465, 2020). "Pathogenic variants in TTN may be an unrecognized cause of skeletal myopathy phenotypes, particularly when accompanied by dilated cardiomyopathy." (PMID 31489791, 2019). "Titin, the largest protein known, has attracted a lot of interest in the cardiovascular field in recent years, since the discovery that truncating variants in titin are commonly found in patients with dilated cardiomyopathy." (PMID 31147888, 2019). "Having a titin-truncating variant may be an independent risk factor for arrhythmia in patients with dilated cardiomyopathy and an implanted cardioverter defibrillator or cardiac resynchronization therapy defibrillator." (PMID 31251381, 2019). "This cohort study investigates the association of titin-truncating genetic variants with life-threatening ventricular arrhythmias in adult patients with dilated cardiomyopathy who have implanted cardiac defibrillators or cardiac resynchronization therapy defibrillators." (PMID 31251381, 2019). "However, TTN codes for the largest known protein and although truncating mutations in TTN are known to cause dilated cardiomyopathy, no such effect of other kinds of mutations are known." (PMID 29897334, 2018). "Titin (TTN) truncating mutations account for 13% in our dilated cardiomyopathy cases (3/23)." (PMID 30165862, 2018). "Nevertheless, successful teams recognized the probable causative nature of the TTN variants in Family 1 based on the fact that one was a published pathogenic change previously reported to cause dilated cardiomyopathy and the second mutation was predicted to alter splicing." (PMID 24667040, 2014). "TTN truncation mutations are a common cause of dilated cardiomyopathy." (PMID 23476865, 2013). "Mutations of titin gene associated with Dilated CardioMyopathy, which is characterized by systolic dysfunction with thinning and expansion of ventricular wall and accounts for up to 50% of cases of heart failure, lead to titin truncation in either its I-band or A-band domains." (PMID 36812205, 2023).
dilated cardiomyopathy (continued). "In addition, TTN is considered as a major determinant of cardiomyocyte stiffness, and mutations in TTN might result in dilated cardiomyopathy in which myocardial stiffness has an important role in its pathogenesis." (PMID 36118869, 2022). "Very recently, TTN (encoding titin protein) truncating mutations were reported to be a common cause of dilated cardiomyopathy, occurring in approximately 25% of familial cases of idiopathic dilated cardiomyopathy and in 18% of sporadic cases where they may represent de novo mutations." (PMID 22830024, 2012). "Mutations in the RNA-binding protein RBM20, which alter its phase separation behavior, lead to aberrant splicing of crucial sarcomeric proteins like titin, resulting in severe dilated cardiomyopathy." (PMID 41596484, 2026). "Within the context of dilated cardiomyopathy (DCM), variants in the TTN gene (the gene that encodes the Titin protein which is the largest protein in the human body) are the most well-known genetic changes that contribute to an individual’s risk of DCM." (PMID 40512817, 2025). "A missense mutation in the titin gene (TTN) and a splice-site mutation in the pyruvate dehydrogenase kinase 4 gene (PDK4) have been associated with dilated cardiomyopathy (DCM) in Dobermanns from the United States." (PMID 40080479, 2025). "We identified patients carrying frameshift variants of TTN (n = 2) and FLNC (n = 1), resulting in truncating proteins, which are classically associated with dilated cardiomyopathy, whereas the association of TTNtv with HCM has been reported only sporadically." (PMID 41440877, 2025). "An estimated 30%–50% of dilated cardiomyopathy (DCM) cases are attributable to genetic factors, with titin (TTN) mutations constituting the most prevalent genetic etiology, accounting for 20%–25% of hereditary DCM cases." (PMID 41306271, 2025). "For instance, Rbm20 knockout mice exhibit dilated cardiomyopathy (DCM) due to the disrupted splicing of genes such as Titin and Camk2d, impairing sarcomere structure and calcium signaling." (PMID 40076920, 2025). "Background/Objectives: Dilated cardiomyopathy (DCM) is a prevalent and life-threatening heart muscle disease often caused by titin (TTN) truncating variants (TTNtv)." (PMID 41283336, 2025). "Genetic factors are estimated to cause approximately 30%–50% of dilated cardiomyopathy (DCM) cases, with Titin (TTN) being the most commonly implicated gene, accounting for 20%–25% of genetic causes." (PMID 40271130, 2025). "TTN truncations are frequently observed in dilated cardiomyopathy (DCM), whereas they are comparatively rare in hypertrophic cardiomyopathy (HCM)." (PMID 41190030, 2025). "By combining volcano plot and GO analysis, we identified differentially expressed genes enriched in hypertrophic and dilated cardiomyopathy, including TTN, TPM3, CTTN, LAMA4, and ITGB1." (PMID 41214391, 2025). "Alternative splicing of the TTN gene plays significant roles in cardiac diseases like dilated cardiomyopathy (DCM)." (PMID 38438525, 2024). "The role of titin in heart diseases, such as dilated cardiomyopathy and heart failure with preserved ejection fraction, as well as its potential as a therapeutic target, is also discussed." (PMID 38660537, 2024). "We also discuss heart diseases in which titin plays a role, such as dilated cardiomyopathy (DCM), heart failure with preserved ejection fraction (HFpEF), and diabetic cardiomyopathy (DbCM)." (PMID 38660537, 2024). "We quantified the expression of ACTN2, ZASP and TTN proteins in two patients with dilated cardiomyopathy and compared them with a sex- and age-matched healthy donor." (PMID 36865889, 2023).
dilated cardiomyopathy (continued). "Truncating variations in the TTN gene termed TTNtv is the most popular reason for heritable dilated cardiomyopathy (HCM)." (PMID 35061126, 2022). "Variants of uncertain significance (VUS) were found in 17 cases (eight resuscitated and nine dead) in genes associated with HCM or dilated cardiomyopathy (DCM), such as TTN, TNNT2, MYH6, DSP, ACTN2, CALR3, and MYH7." (PMID 36588553, 2022). "Titin stiffening is associated with the development of diastolic dysfunction (DD), while augmented titin compliance appears to impair systolic performance in dilated cardiomyopathy." (PMID 35575093, 2022). "The results showed that genes (DES, MYH6, MYL2, MYL3, TPM1, TPM3, TPM4, and TTN) in MCODE 2 were significantly involved in dilated cardiomyopathy and hypertrophic cardiomyopathy (HCM)." (PMID 35645614, 2022). "In this article, we review titin’s contribution to normal cardiac physiology, the pathophysiology of titin truncation variations leading to dilated cardiomyopathy, and transcriptional and post-translational modifications of titin." (PMID 32859027, 2020). "Although patients with CCM had rare variants in several established dilated cardiomyopathy (DCM) genes (BAG3, LMNA, MYH7, TCAP, TNNT2, and TTN), only variants in TTN, which encodes titin, were significantly increased." (PMID 30987448, 2019). "For example, RBM20 is crucial for the formation of a subset of circRNAs that originate from the I-band of the titin gene, and these circRNAs are dynamically regulated in dilated cardiomyopathy." (PMID 30531834, 2019). "Pathogenic variants in TTN (OMIM 188840), encoding the largest human protein, are known to cause dilated cardiomyopathy and several forms of skeletal myopathy." (PMID 31489791, 2019). "Titin isoform transitions have occurred in a number of cardiac diseases, such as dilated cardiomyopathy, diabetic cardiomyopathy, ischemic heart failure, and hypertrophic cardiomyopathy." (PMID 31614708, 2019). "To investigate the role of apoptosis in TTN-based dilated cardiomyopathy, we used an inducible DCM mouse model with a human TTN truncation mutation." (PMID 28353642, 2017). "The authors show that the length of thick filaments is defined by titin, and that alterations in titin length affect force generation and lead to dilated cardiomyopathy in mice." (PMID 29051486, 2017). "A 36-year-old woman with nonischemic dilated cardiomyopathy (DCM) due to a pathogenic titin (TTN) truncating variant presented in cardiogenic shock with progressive dyspnea and chest discomfort." (PMID 40970862, 2025). "Association of the TTN and PDK4 variants with dilated cardiomyopathy." (PMID 40080479, 2025). "Moreover, isogenic hiPSC-CMs containing a rare E1 variant in the predicted MEF2-binding motif that was identified in a patient with unexplained dilated cardiomyopathy (DCM) showed reduced TTN expression." (PMID 39688912, 2024). "For instance, truncating variations in the TTN gene are known to be the most frequent type of variations causing dilated cardiomyopathy rather than missense variations." (PMID 39434095, 2024). "Mortality in this group was around 3% in titin dilated cardiomyopathy patients." (PMID 38999368, 2024). "Titin (TTN) is one of the largest and most complex proteins expressed in humans, and truncation variants are the most prevalent genetic lesion identified in individuals with dilated cardiomyopathy (DCM) or other disorders of impaired cardiac contractility." (PMID 38226618, 2024). "Thus, we assumed that TTN c.13254T>G was a pathogenic cause of DCM, and developed a mouse model of dilated cardiomyopathy carrying the mutant to supplement and improve the functional evidence of the rare variant TTN c.13254T>G." (PMID 38381767, 2024). "For example, most individuals carrying a truncating variant in TTN do not have, and will not develop, dilated cardiomyopathy." (PMID 37285546, 2023).